CRP (C-reactive protein)
Diseases named in the same sentence as CRP in open-access papers (continued):
Sharing a sentence is not in itself a finding about the gene and the disease.
depression (continued). "We provide evidence that, out of all cardiovascular risk factors, triglycerides and the inflammatory markers IL-6 and CRP are likely to be causally related to depression." (PMID 30886334, 2020). "Belonging to the medium-to-high CRP trajectory was associated with higher odds of depression (OR = 1.55; 1.13, 2.12)." (PMID 29462285, 2019). "This study aimed to investigate the sex difference in the association between hs-CRP and depression." (PMID 30760746, 2019). "For example, a study in Japanese patients with RA revealed a significant association between both depression score and C-reactive protein levels with pain." (PMID 31673680, 2019). "For example, major depressive disorder has been associated with increased serum acute phase reactants and proinflammatory cytokines such as C-reactive protein (CRP), interleukin (IL)-6, IL-1β, and tumor necrosis factor (TNF)." (PMID 31631951, 2019). "Multiple large studies have consistently shown that there is an inverse, independent, dose–response relation between level of PA and immune cytokines (e.g., IL-6 and CRP), while depression is associated with increased plasma levels of immune cytokines." (PMID 30046989, 2019). "A systematic review and meta-analysis of 32 studies also supported an association of both CRP and IL-6 with depression in older adults, and it is likely that inflammation leads to depression." (PMID 30995920, 2019). "For example, in a study implicating 210 non-smoking healthy and unmedicated adult men and women, poor sleep quality was associated with higher values of CRP and IL-6 in women only, after adjustment for age, BMI, and symptoms of depression." (PMID 31287027, 2019). "The association between BMI and hs-CRP in depression was only found in the “normal weight” group in men." (PMID 30760746, 2019). "In a study using combined data of two Copenhagen population-based studies of 73,131 samples, elevated CRP levels were associated with increased risk for depression after adjusting for covariates including sex9." (PMID 30760746, 2019). "Associations have been shown between depression and serum levels of CRP, IL-1β, IL-1RA, and MCP-1 in type 2 diabetes patients, with all serum levels being significantly higher in those who are depressed." (PMID 31379879, 2019). "Elevated levels of circulating CRP have been observed in depression, but the exact association between high CRP and depression is unclear." (PMID 30760746, 2019). "The results of the present analysis provide further insight and show that relatively low baseline CRP but increasing over time is associated with subsequent depression." (PMID 29462285, 2019). "Atypical features of depression, particularly increased appetite or weight, are associated with a number of genetic risk variants for body mass index (BMI) and levels of CRP and leptin." (PMID 30414442, 2019). "Using Mendelian randomisation analysis of the UK Biobank sample, we previously found that out of all cardiovascular risk factors, IL-6, CRP and triglycerides are likely to be causally linked with depression." (PMID 31258105, 2019). "A 1-year observation showed that major depression was strongly associated with increased levels of CRP in men13." (PMID 30760746, 2019). "Several studies have investigated the association between depression and CRP according to sex, but the results are conflicting." (PMID 30760746, 2019). "Using longitudinal data from a general population-representative birth cohort, we have examined associations between childhood IL-6 and CRP levels and specific symptoms of depression in early adulthood." (PMID 30414442, 2019). "Depression status was assessed from the World Health Organization Composite International Diagnostic Interview and inflammation status was measured based on C-reactive protein (CRP) concentrations." (PMID 31109116, 2019).
depression (continued). "In conclusion, depression was considerably associated with hs-CRP only in men, even after adjusting for age, BMI, and other variables known to affect low-level inflammation." (PMID 30760746, 2019). "MDD is associated with increased CRP compared with healthy volunteers and the case–control difference appears higher in treatment-resistant depression." (PMID 29764522, 2019). "This study aimed to examine the serum levels of interleukin-6 (IL-6) and C-reactive protein (CRP) in MDD patients to find out their association with depression." (PMID 30899619, 2019). "Increased CRP levels have been previously associated with depression, and a recent study found that the effectiveness of the antidepressant, agomelatine, was associated with a reduction in CRP levels." (PMID 29747386, 2018). "Prospective cohort studies indicate a correlation between elevated levels of IL-6/CRP and subsequent risk of physical and neuropsychiatric illnesses such as cancers, coronary heart disease, type 2 diabetes, Alzheimer's disease, depression and psychosis." (PMID 29198208, 2018). "Specifically, CRP, elevated levels of which have been increasingly identified as a risk factor for depression, was associated with increased odds only among whites." (PMID 30154326, 2018). "We report that the variant is associated with increased IL-6 but decreased CRP levels assessed in childhood, and is protective for severe depression and/or psychosis assessed in early adulthood." (PMID 29197507, 2018). "In depressed patients, elevated CRP levels have been associated with higher likelihood of hospitalization related to depression." (PMID 29329256, 2018). "Elevated IL-6 and/or CRP has been associated with depression, autism, schizophrenia and related psychoses." (PMID 29198208, 2018). "In a study performed on 80 patients, elevated levels of CRP were associated with depression and anxiety." (PMID 29619128, 2018). "When those with CRP levels ≥10 mg/l were excluded, the association between sleep disturbance and depression remained (adjusted OR = 1·77, 95% CI 1·33, 2·34)." (PMID 30249545, 2018). "A double-blind, placebo-controlled, randomized trial with anti-TNFα Ab infliximab in 60 patients with major depression showed an association between baseline levels of the inflammatory marker CRP and the response to infliximab." (PMID 30423923, 2018). "Of the clinical indicators, only C-reactive protein levels were associated with active depression in lupus." (PMID 30148175, 2018). "CRP and depression have been the focus of past studies, with some showing a positive association between depression and inflammation." (PMID 28762106, 2018). "Other meta-analyses have suggested associations between depression and inflammatory markers, such as C-reactive protein (CRP), IL-6 and, to a lesser extent, IL-1." (PMID 30400354, 2018). "Adjusting for age, socioeconomic status, and all other biomarkers, high-risk CRP, serum album, and total cholesterol levels, as well as high-risk pulse rate were differentially associated with increased risk for depression across the four groups." (PMID 30154326, 2018). "A meta-analysis indicated that the inflammatory markers associated with depression are TNFα, IL-1, IL-6 and CRP and there are many reports showing the association between serum IL-6 increase and depression." (PMID 30423923, 2018). "Higher baseline CRP levels are associated with improvements in depressive symptoms in treatment resistant depression treated with infliximab, an anti-TNF-α monoclonal antibody." (PMID 29544672, 2018). "A study performed on 73,131 participants showed that elevated CRP levels are associated with a high risk of psychological distress and depression." (PMID 29619128, 2018). "We have examined the association of Asp358Ala with diagnosis of depression and psychosis, serum IL-6, CRP levels, and a number of risk factors commonly linked with inflammation, depression or psychosis." (PMID 29197507, 2018).
depression (continued). "Longitudinal studies including our own have shown that elevated IL-6 or CRP levels are associated with increased risks of developing depression and psychosis in future." (PMID 29140226, 2018). "Reinforcing the link between inflammation and depression, genetic studies have shown that mutation in inflammatory-related genes (such as CRP or IL-6) increased the risk on MDD onset." (PMID 29615964, 2018). "Third, the comprehensive set of sociodemographic, lifestyle, physical, metabolic and other factors related to depression provide adequate qualification to evaluate the association between serum CRP concentrations and depression." (PMID 28128231, 2017). "Pearson partial correlational analysis revealed that there were significant associations between CM score and CRP (r = 0.21, p = 0.04), and TNFα (r = 0.23, p = 0.02), after adjusted by age, gender, race, education, and depression symptoms." (PMID 28713332, 2017). "The positive CRP-depression association that existed only in the underweight group in our study provided mixed evidence of the inflammation-depression research." (PMID 28128231, 2017). "Low birth weight (a marker of suboptimal foetal development) and childhood maltreatment are associated with increased circulating CRP levels as well as risks of heart disease, diabetes mellitus, depression and schizophrenia." (PMID 28418288, 2017). "Our result of an association between CRP and age of depression onset supports previous findings from the Netherlands Study of Depression and Anxiety (NESDA) including a large sample of patients with depression." (PMID 29218020, 2017). "We have previously shown that heightened C-reactive protein levels in response to CABG surgery mediated the association between depression and longer hospital stays." (PMID 27552993, 2017). "Women homozygous for the minor allele of rs1205 (TT) were more likely to suffer depression, but had lower circulating levels of CRP." (PMID 27555379, 2017). "Many previous studies have estimated the association between depression and serum CRP either cross-sectionally or longitudinally." (PMID 28128231, 2017). "Instead, the rs1205(G/A) polymorphism, which was associated with lower concentrations of serum CRP, was associated with an increase in the risk of depression." (PMID 27555379, 2017). "Two studies have shown that genetic variations in CRP are associated with depression in the context of the metabolic syndrome." (PMID 27555379, 2017). "The data suggest that the association between depression and inflammation seems to be stronger for IL-6 than CRP." (PMID 25877654, 2016). "For example, chronically elevated IL-6 levels have been associated with psychological disorder (particularly depression) and changes in immune markers CRP and cortisol have been associated with loneliness longitudinally." (PMID 27367428, 2016). "Previous researches reveal that depression is associated with increased inflammatory markers including C-reactive protein (CRP), interleukin-1, and interleukin-6." (PMID 27955661, 2016). "Scattered reports also exist of inverse associations between CRP levels and cognitive function in severe depression, and in bipolar disorder." (PMID 26973142, 2016). "Our finding that current depression is associated with higher CRP in females is helpful since some recent population-based studies found sex differences in associations between depression and CRP, such that the relationship was only found for men." (PMID 27493807, 2016). "For example, C-reactive protein (CRP) has been used as a biomarker to predict depression, and the increased CRP expression level was identified as an independent risk factor for de novo depression in women." (PMID 27917343, 2016). "Associations have been reported between IL-6 or CRP and depression, hopelessness, vital exhaustion, negative affect, and psychological distress." (PMID 26979423, 2016).
depression (continued). "We previously reported that PTSD, depression, and insomnia in military personnel are associated with higher concentrations of inflammatory proteins including C-reactive protein (CRP), and that improved sleep resulted in reductions in inflammation." (PMID 25983695, 2015). "Previously, we reported that depression and insomnia in military personnel are associated with higher concentrations of CRP, and that improved sleep reduces inflammation." (PMID 25983695, 2015). "Other studies showed that clinical depression and depressive symptoms are positively correlated with CRP levels after controlling for age, gender, BMI, high density lipoprotein cholesterol concentrations, and other traditional risk factors of depression." (PMID 25793613, 2015). "We found a weak association between CRP levels and fatigue scores at six months, but this association disappeared after controlling the effects of anxiety, depression, and daily step counts, with anxiety as the only significant association." (PMID 26599129, 2015). "Meta-analyses have indicated that the most robust evidence-based inflammatory markers associated with depression include interleukin-6 (IL-6), C-reactive protein (CRP), and TNF-a." (PMID 26617482, 2015). "Conversely, incident storage LUTS was predicted by the presence of both anxiety and depression at baseline, an effect which showed an age-adjusted association with higher CRP." (PMID 26445118, 2015). "A recent longitudinal study conducted in England revealed that children with elevated serum IL-6 and CRP levels were more at risk to develop depression and psychosis later in life." (PMID 26217190, 2015). "These analyses revealed that the association between IL-6, CRP and major depression remained strong and unaltered in studies of higher quality and antidepressant-free patients." (PMID 26065825, 2015). "Subgroup analysis showed that the associations of IL-6 and CRP concentrations with major depression remained relatively stable when assessing the effect of age, gender, BMI, study size or study quality on overall effect estimate." (PMID 26065825, 2015). "In the second study, Poole and colleagues found that elevated hs-CRP levels at postoperative day four mediated the association between depression and an increased length of stay." (PMID 25329583, 2014). "The results of their study showed that the serum concentration of CRP is only weekly associated with depression scores in later life." (PMID 25237581, 2014). "A second limitation of this study is the lack of a comparison between suPAR measurements and other components of the fibrinolytic system or other inflammatory markers previously shown to be associated with depression, such as CRP or IL-6." (PMID 25329298, 2014). "Our findings are in line with studies of depression and CRP that found an association between CRP levels and prior depression." (PMID 25329298, 2014). "Similar associations between depression and C-reactive protein (CRP), IL-6, and, to a lesser extent, IL-1 have been found in patients with cardiac disease or cancer." (PMID 24723864, 2014). "Inflammatory markers, such as interleukin-6 and C-reactive protein, have also been associated with poorer performance on tests of psychomotor speed and verbal memory in individuals with depression." (PMID 24996486, 2014). "Overall, MBTs were positively associated with decreased CRP levels in patients with type 2 diabetes, cancer, or heart failure, and the elderly with depression and cardiovascular disease risk factors." (PMID 24988414, 2014). "This study aimed to explore the role of C-reactive protein (CRP) in mediating the association between greater pre-operative depression symptoms and longer post-operative length of stay in patients undergoing coronary artery bypass graft (CABG) surgery." (PMID 24239712, 2014). "Depression in general and major depressive disorder in particular has been linked with acute phase inflammatory mediators including CRP." (PMID 23857873, 2014).
depression (continued). "This is consistent with the work of others who found that higher CRP levels were associated with depression and worse cognitive functioning." (PMID 24661373, 2014). "This study is the first to our knowledge which has prospectively examined the association between depression and CRP and their impact on physical recovery in a CABG population." (PMID 24239712, 2014). "C-reactive protein (CRP) is a marker of low-grade inflammation, prospectively associated with increased risk of both cardiovascular disease and depression." (PMID 25237581, 2014). "Elevated pro-inflammatory cytokines, such as IL-6 and TNF-α, along with CRP have been found in depressive patients; however, the association between CRP and depression is controversial." (PMID 27429271, 2014). "In the Cardiovascular Health Study of 4 268 patients, a significant association was noted between high levels of C-reactive protein and depression symptoms, even after adjusting for confounding factors." (PMID 25226167, 2014). "For example, elevated serum levels of TNF-α, IL-6, and interleukin-10 (IL-10) have been reported during the early stages of bipolar disorder, and CRP appears to be a biomarker of de novo depression risk." (PMID 24782789, 2014). "Other studies also indicate an association between depression and increased activity of acute phase proteins and inflammatory molecules, including CRP." (PMID 24170724, 2013). "In studies of diabetic patient cohorts, the inflammatory marker CRP was consistently predictive of direct associations between depression severity, lipid profiles and obesity levels." (PMID 24385966, 2013). "Cigarette smoking has also been associated with raised levels of C-reactive protein, suggesting the stimulation of a chronic inflammatory state, which again, is described in both depression and cardiovascular disorders." (PMID 23705944, 2013). "With respect to inflammation, only the somatic symptom dimension of depression was consistently associated with elevated levels of IL-18, IL-1-Ra, fibrinogen, CRP and decreased albumin levels." (PMID 23967272, 2013). "We considered earlier the evidence that there is a form of inflammation-associated depression, accompanied by raised CRP and IL-6, that is common in rich urban societies, but probably rare in low-income countries." (PMID 24481186, 2013). "In combination with the observed link between increased C reactive protein and subsequent depression, this has given rise to a theory implying a possible role for cytokines and other immune components in depression, either as a cause or as an epiphenomena." (PMID 23118981, 2012). "Higher CRP plasma levels have been shown to be associated with both the metabolic syndrome and depression and anxiety, although some studies failed to confirm these associations." (PMID 21296145, 2011). "Several studies had previously examined the association between CRP and depression, and the preponderance of evidence supports the conclusion that depression is associated with increase in CRP but was confounded or mediated by other variables." (PMID 21701640, 2011). "Depression is associated with the development of the metabolic syndrome, and both depression and metabolic syndrome are associated with markers of systemic inflammation, such as C-reactive protein (CRP)." (PMID 21296145, 2011). "A recent meta-analysis on inflammatory markers in depressed patients has confirmed a consistent positive association between depression and IL-6, and IL-1 and the acute phase protein CRP levels in peripheral blood." (PMID 20161799, 2010). "The study provides preliminary support for the notion that high harm avoidance and low self-directedness are indeed associated with elevated CRP in middle-aged women recruited from the general population and negating ongoing depression." (PMID 18384670, 2008). "Although the literature is not unanimous, a large number of studies suggest that ongoing depression is associated with elevated levels of CRP." (PMID 18384670, 2008).